MYC (MYC proto-oncogene, bHLH transcription factor)
Diseases named in the same sentence as MYC in open-access papers (continued):
Sharing a sentence is not in itself a finding about the gene and the disease.
colon carcinoma (480 papers, 2003 to 2026). "For instance, high c-MYC expression in colon cancer is strongly associated with tumor recurrence in patients undergoing adjuvant chemotherapy with 5-fluorouracil." (PMID 38163859, 2024). "Amplification of MYC gene also occurs in colon cancer, apart from direct transcriptional MYC activation caused by the WNT/β-catenin signaling pathway." (PMID 36969025, 2023). "In relation to uPAR signaling, MYC downregulated the uPA system to reduce cell motility and invasiveness in gastric cancer, while silencing uPAR was associated with decreased c-MYC expression in melanoma and colon cancer." (PMID 37895906, 2023). "MYC dysregulation is associated with aggressive biological behavior and adverse clinical outcome of colon cancer." (PMID 35120580, 2022). "This enzyme has been poorly studied in cancer, however, a recent report indicated that the proto-oncogen MYC induces AFMID expression in colon cancer, and it is associated with cell proliferation through an AhR modulation by KYN." (PMID 36355137, 2022). "Another analysis based on the TCGA found that KLK6 overexpression correlated with c-MYC expression and both are associated with overall survival of patients with colon cancers." (PMID 35883559, 2022). "Corroborating findings were reported in a previous research that c-MYC was upregulated in CD133 colon cancer stem cells, and that upregulated c-MYC caused cell proliferation and chemoresistance of colon cancer." (PMID 34921134, 2021). "MYC (mainly c-MYC) is overexpressed in most human colon cancers, which is associated with carcinogenesis, tumorigenesis and progression." (PMID 33170148, 2020). "If Lnc-EPIC1-induced colon cancer cell progression is due to association with MYC, it should be ineffective in MYC-depleted cells." (PMID 33170148, 2020). "Knocking down MYC or LEF1 caused a dramatic reduction in the viability of the colon cancer cells DLD1 and RKO." (PMID 31623618, 2019). "We first investigated HUGL-1, YAP, c-MYC and activated Caspase 3 (hereafter referred to as Cas3) distribution in colon cancers, where HUGL-1 alterations have been associated with malignant progression." (PMID 28974715, 2017). "In contrast, the Myc mRNA and protein over-expression that is observed in 70-80% of colon carcinomas results from aberrant transcriptional control of the MYC locus involving mutations in APC-b-catenin-TCF-4 pathway members." (PMID 22373487, 2012). "We investigated here two 8q24 breast and colon cancer risk alleles in the close vicinity of the MYC gene for their role in the occurrence of distant metastases." (PMID 22666420, 2012). "al. have clearly shown using 3C analysis that the colon cancer risk region can physically interact with numerous elements on chromosome 8q24 in addition to the MYC promoter." (PMID 21533051, 2011). "Because positioning of the distal elements A-E with the MYC promoter was detected in non-colon cancer cells lines that lack chromatin associated ß-catenin/TCF4 complexes, it is unlikely that these factors are required to form the chromatin loops." (PMID 21533051, 2011). "For instance, the proto-oncogene MYC has been associated with liver metastases in colon cancer." (PMID 40642075, 2025). "Further studies will be needed to explore whether LncRNA EPIC1 expression and its association with MYC are important for the growth of colon cancer cell in vivo, for example using a mouse subcutaneous colon cancer model." (PMID 33170148, 2020). "They found that MYC increased intracellular levels of tryptophan and tryptophan metabolites in the kynurenine pathway and that blocking the kynurenine pathway caused preferential death of established colon cancer cells and transformed colonic organoids." (PMID 31416966, 2019). "Since loss of PVT1 RNA in colon cancer cell line reduces MYC protein to more normal levels, inhibiting PVT1 could be a more accessible and feasible therapeutic strategy for renal cancer." (PMID 27366943, 2016).
colon carcinoma (continued). "Similarly, the 8q24.21 region of association defined by rs1948915, which contains CCAT1 (colon cancer-associated transcript 1), interacts with MYC and distal upstream enhancer elements." (PMID 27363682, 2016). "Reverse genetics of the human lncRNAome has yielded a conserved lncRNA, CCAT, which overlaps a colon cancer susceptibility SNP, regulates MYC, and causes a two-fold difference in invasiveness and a four-fold difference in liver metastasis in a mouse colon cancer model." (PMID 25699073, 2014). "In colon cancer, high expression of the MYC transcript significantly correlated with tumor recurrence in patients who underwent adjuvant 5‐fluorouracil (5FU) chemotherapy, an association attributed to the MYC‐dependent activation of the ABC‐family transporter ABCB5." (PMID 36214609, 2022). "Therefore, c-MYC may be implicated in the chemoresistance of colon cancer, which needs to be further verified." (PMID 34921134, 2021). "The results revealed that NKD1 and MYC were expressed at low levels in normal tissue and highly expressed in colon cancer tissues." (PMID 40675969, 2025). "Further study revealed that the MYC protein was degraded mainly through the autophagy pathway in colon cancer cells and that NKD1 restrained this process by suppressing the interaction between LC3B and MYC proteins." (PMID 40675969, 2025). "In contrast, SW620-nkd1−/− cells demonstrated markedly lower MYC expression than that in SW620 cells, indicating that NKD1 increases MYC protein expression levels in colon cancer cells." (PMID 40675969, 2025). "Taken together, these findings indicate that the NKD1/MYC signaling pathway promotes the proliferation, migration, and angiogenesis of colon cancer cells." (PMID 40675969, 2025). "For this purpose, three colon cancer cell lines from the NCI-60 panel with different MYC gene copy numbers were used." (PMID 40940795, 2025). "Research has shown that NKD1 knockout significantly reduces the expression of the MYC protein and that there is a significant positive correlation between the expression of NKD1 and that of MYC in colon cancer tissues." (PMID 40675969, 2025). "The results revealed a significant positive correlation between NKD1 and MYC gene expression in colon cancer tissues (p < 0.05)." (PMID 40675969, 2025). "Functionally, the PPARδ/NKD1/MYC signaling pathway increased colon cancer cells’ proliferation, migration and angiogenesis capabilities." (PMID 40675969, 2025). "To this end, we employed three colon cancer cell lines from the NCI-60 panel with different MYC copy numbers (HCT-15: 2 copies, HT-29: 4 copies, and SW-620: 7 copies), applying the same transfection conditions established in MCF7." (PMID 40940795, 2025). "Collectively, these results suggest that the interaction between CREPT and MYC is critical for the tumorigenesis of colon cancer cells." (PMID 39615685, 2024). "In particular, we found that the expression of CREPT and MYC correlated with colon cancer, with rho = 0.476." (PMID 39615685, 2024). "MYC was significantly regulated in colon cancer cells with restricted or enhanced expression of PUS7." (PMID 39162904, 2024). "The universal oncogene MYC transcription in colon cancer cells first induces the particular profile of AHR in that cancer; AHR then promotes MYC-induced proliferation by turning on the expression of the genes needed for biomass generation." (PMID 39201782, 2024). "Lon protease was purified for recombinant expression and delivered into mouse models of MYC-dependent bladder and colon cancer via peroral or intravenous routes." (PMID 37450923, 2024).
colon carcinoma (continued). "To investigate the interaction between CREPT and MYC during different cell cycle stages, we performed an immunoprecipitation experiment in synchronized colon cancer cell lines." (PMID 39615685, 2024). "HTLV-1 Tax acts on genes indirectly by binding several TFs, such as TCF3, ELK1, and MYC in colon cancer, as well as POLB, BUB3, and CDK4, according to the HTLV-1 infection signaling pathway." (PMID 39228892, 2024). "Of them, 14 lncRNAs are verified in databases C and D. found that lncRNA PVT1 increases MYC protein level, which in turn increases the cancer rate of colon cancer." (PMID 37614816, 2023). "To gain additional mechanistic insights, we examined the effects of βPix deficiency on several genes associated with colon cancer progression; c-MYC, CCND1, and PTGS2, which encode c-Myc, β-catenin, and cyclooxygenase-2." (PMID 37805544, 2023). "Successful downregulation of MYC mRNA and protein has been demonstrated using LipofectamineTM-mediated delivery of siRNA in colon cancer cells, leading to proliferation inhibition, induction of apoptosis, and cell growth suppression." (PMID 36969025, 2023). "Further supporting this finding, eccDNA containing amplified forms of MYC has been observed in a variety of tumor types, including acute myeloid leukemia, granuloma carcinoma, colon cancer, and ovarian cancer." (PMID 39534571, 2023). "SULT2B1 expression was diminished by downregulating c-MYC, thereby restraining glycolytic metabolism to inhibit colon cancer cell proliferation and chemoresistance under condition of knockdown of OLR1." (PMID 37337170, 2023). "LINC00941 is upregulated in colon cancer and was shown to sponge miR-205-5p, leading to increased expression of MYC." (PMID 36869839, 2023). "Noteworthy is the observation that the most sensitive cell lines (hematopoietic and colon cancers) are those characterized by higher c-MYC expression levels." (PMID 36536122, 2023). "Overexpression of MYC in human colon cancer and esophageal cancer cells promotes the expression of HIF1A at the post-transcriptional level." (PMID 37998757, 2023). "To further test the applicability of the CGE method for studying precise mutations in diploid cells, we performed ChIP using anti-MYC and anti-H3K27ac antibodies after precision editing of the MDN1 locus in HCT116 colon cancer cells." (PMID 36163549, 2023). "Gene-gating of a MYC oncogenic super-enhancer (OSE) increases its expression in colon cancer cells in a poorly understood process." (PMID 35017527, 2022). "It demonstrated that K-Ras conferred SAHA resistance by upregulating HDAC6 and MYC expression in colon cancer cells." (PMID 35591851, 2022). "CNVs specific for MSS colon cancer IntOMICS identified edges from CNV to associated GE in five out of six genes of interest: KRAS, MYC, BIRC5, RAC3, and SMAD4." (PMID 35996085, 2022). "In colon tumors from ApcMin/+ mice loss of DRO1/CCDC80 induces ERK1/2 phosphorylation and leads to c-MYC oncogene activation." (PMID 35422964, 2022). "In order to study the role of MYC in colon cancer cells, MYC over-expressing HCT116 and Caco-2 cells were constructed." (PMID 35120580, 2022). "As colon cancer develops, mutations in the WNT pathway lead to an increase of MYC, which results in small adenoma formation." (PMID 35159051, 2022). "A colon cancer-associated single nucleotide variant in this binding site increases the binding of TCF7L2 and the expression of MYC." (PMID 36067202, 2022). "Our study proposes the clinical potential of cordycepin in treating colon cancer by targeting the MYC/miR-26a pathway." (PMID 35120580, 2022). "High MYC protein expression in primary colon cancer was also predictive of an inferior response to anti‐EGFR monoclonal antibodies plus FOLFIRI (a polychemotherapy regimen based on 5FU and irinotecan)." (PMID 36214609, 2022).
colon carcinoma (continued). "Abnormal WNT signaling increases MYC expression in colon cancer cells in part via oncogenic super-enhancer-(OSE)-mediated gating of the active MYC to the nuclear pore in a poorly understood process." (PMID 35017527, 2022). "The obtained results showed that in HCT116 colon cancer cells treated with UA compounds, the MYC expression strongly increased after 72 h of incubation and remained at a similar level after 120 h." (PMID 35328482, 2022). "Cordycepin is able to suppress colon cancer cell proliferation, likely mediated by the MYC/miR-26a pathway, supporting its potential for the treatment of colon cancer." (PMID 35120580, 2022). "On the other hand, the depletion of c-MYC has been shown to diminish ribosome production in colon cancer." (PMID 35267559, 2022). "Ubiquitous inactivation of Dro1/Ccdc80 leads to increased phosphorylation of ERK1/2 and oncogenic c-MYC activation in colon tumors from ApcMin/+ mice." (PMID 35422964, 2022). "Consistently, we demonstrated ubiquitous inactivation of Dro1/Ccdc80 to implicate increased c-MYC protein levels in the colonic epithelium and in colon tumors from ApcMin/+ mice." (PMID 35422964, 2022). "Cordycepin inhibited colon cancer cell proliferation by down-regulating MYC mRNA/protein expression and up-regulating miR-26a in both HCT116 and Caco-2 cells." (PMID 35120580, 2022). "While it is worth noting that, as a proto-oncogene and a classical Wnt pathway target gene, enhanced and/or altered expression of MYC expression are universally present in colon cancer." (PMID 35120580, 2022). "Previously we have shown activation of both pERK1/2 and oncogenic c-MYC in colon tumors from ApcMin/+ mice upon ubiquitous inactivation of Dro1/Ccdc80." (PMID 35422964, 2022). "A similar finding was noted in our work that OLR1 knockdown diminished c-MYC expression to suppress colon cancer cell glycolytic metabolism, proliferation, and chemoresistance." (PMID 34921134, 2021). "In colon cancer cell lines overexpressing MYC, camptothecin treatment results in effective apoptosis induction, indicating MYC overexpression contributes to colon cancer cells sensitization to this agent." (PMID 34372899, 2021). "Immunohistochemistry authenticated that compared with adjacent normal tissues, c-MYC was substantially upregulated in colon cancer tissues, which was mainly located in the nucleus of colon cancer tissues." (PMID 34921134, 2021). "Existing literature has suggested that ectopically expressed c-MYC facilitates glucose metabolism, viability, and migration of colon cancer cells." (PMID 34921134, 2021). "Results showed increased expression levels of the MYC/CXCL8/TIMP1 oncogenes across colon cancer cell lines." (PMID 34440739, 2021). "For example, Linc-RoR lncRNA stabilizes MYC gene mRNA in colon cancer cells by controlling its interaction with AU-rich element RNA-binding protein 1 (AUF1) and heterogeneous nuclear ribonucleoprotein I (hnRNPI)." (PMID 34440124, 2021). "Overexpression of SULT2B1 neutralized the sensitization effect of colon cancer cells to chemotherapeutic drugs induced by c-MYC knockdown." (PMID 34921134, 2021). "Study of other genes revealed that LMNB2 showed an interaction with the MYC gene, and the overexpression of this nuclear protein was reported to inhibit colon cancer cell migration and interaction with chromatin." (PMID 34830168, 2021). "On the basis of detection result, the ECAR, glucose intake, lactate production, ATP/ADP ratio, and GLUT1 and LDHA expression of LoVo colon cancer were apparently diminished by knocking down c-MYC." (PMID 34921134, 2021). "For another RNA, circCCDC66, the ability to up-regulate MYC gene expression in colon cancer cells through the binding of miR-33b and miR-93 was shown." (PMID 34440124, 2021). "Meanwhile, MTS assay, clone formation assay, and RT-qPCR manifested that overexpression of SULT2B1 negated the repressive effect of c-MYC knockdown on colon cancer cell proliferation." (PMID 34921134, 2021).
colon carcinoma (continued). "In order to further verify that OLR1 regulated the proliferation and chemoresistance of colon cancer cells by promoting c-MYC, OLR1 was knocked down and/or c-MYC was overexpressed in colon cancer cells." (PMID 34921134, 2021). "Others have shown that c-MYC can independently induce TfR138 and that transfection of c-MYC to colon cancer cell lines increases ferritin heavy chain transcription." (PMID 34211054, 2021). "The obtained data in our research manifested that knockdown of c-MYC depressed the proliferation and chemoresistance of colon cancer cells by diminishing glycolytic metabolism via SULT2B1 downregulation." (PMID 34921134, 2021). "Recently, we reported a significant survival-decreasing effect in primary human colon cancer stem-like cells by the inhibition of MYC signaling using KJ-Pyr-9." (PMID 33925297, 2021). "We found that MYC promotes the import of tryptophan into colon cancer cells by transcriptionally driving the expression of SLC7A5 and SLC1A5, which are capable of transporting tryptophan." (PMID 31922097, 2020). "CRISPR/Cas9-induced MYC KO significantly inhibited colon cancer cell survival, proliferation and migration." (PMID 33170148, 2020). "Because MYC was shown to be indispensable for colon cancer initiation in animal models and because MYC expression is elevated in almost all colon cancers samples, we predict that kynurenine levels will be globally elevated in colon cancer patients." (PMID 31922097, 2020). "PVT1 depletion in HCT 116 colon cancer cells dramatically compromised their ability to form tumors, as high MYC protein levels are dependent on PVT1." (PMID 32602581, 2020). "RNA-immunoprecipitation and RNA pull-down results confirmed that Lnc-EPIC1 directly binds MYC protein in colon cancer cells." (PMID 33170148, 2020). "For example, a NOTCH-bound MYC enhancer played essential roles in the T-Cell Acute Lymphoblastic Leukemia, while in colon cancer, MYC expression was concurrently regulated by enhancers and complexes." (PMID 31665430, 2020). "To investigate the role of RNF8 in colon cancer, we first analyzed its expression along with that of oncogene MYC, which is frequently dysregulated in colon cancer 26, in 478 colon cancer patients and 41 normal controls based on the TCGA database." (PMID 32549753, 2020). "Consistent with the TCGA data, the protein levels of RNF8 and MYC gene in colon cancer tissues were both significantly higher than those in benign tissues, as indicated by analysis of the staining scores." (PMID 32549753, 2020). "In particular, in colon cancer cells, Elys binds the oncogenic super enhancer and directs it to the NPC-linked MYC gene, which drastically increases nuclear export of MYC mRNAs." (PMID 33322130, 2020). "In this study, RIP and RNA pull down assay results confirmed that Lnc-EPIC1 directly binds MYC protein in the primary human colon cancer cells, essential for MYC’s function." (PMID 33170148, 2020). "To further support Lnc-EPIC1-mediated colon cancer cell progression is due to MYC association, we show that CRISPR/Cas9-inudced MYC KO mimicked Lnc-EPIC1 silencing-induced activity and inhibited colon cancer cell survival, proliferation and migration." (PMID 33170148, 2020). "The results showed that the mRNA level of RNF8 was elevated in colon cancer tissues compared with normal controls, as well as that of MYC." (PMID 32549753, 2020). "More importantly, in MYC-KO colon cancer cells Lnc-EPIC1 siRNA or overexpression was completely ineffective on cell behaviors." (PMID 33170148, 2020). "Different studies have demonstrated that the oncoprotein c-MYC is frequently activated in tumour cells (either in colon cancer or in other tumour types)." (PMID 32977434, 2020). "We have recently found that this principle involves the gating of MYC to nuclear pores mediated by an oncogenic super-enhancer in a ß-catenin-dependent manner in colon cancer cells." (PMID 32158925, 2020).